DYRK3 (dual specificity tyrosine phosphorylation regulated kinase 3)
Description:
Dual-specificity protein kinase that promotes disassembly of several types of membraneless organelles during mitosis, such as stress granules, nuclear speckles and pericentriolar material. Dual-specificity tyrosine-regulated kinases (DYRKs) autophosphorylate a critical tyrosine residue in their activation loop and phosphorylate their substrate on serine and threonine residues. Acts as a central dissolvase of membraneless organelles during the G2-to-M transition, after the nuclear-envelope breakdown: acts by mediating phosphorylation of multiple serine and threonine residues in unstructured domains of proteins, such as SRRM1 and PCM1. Does not mediate disassembly of all membraneless organelles: disassembly of P-body and nucleolus is not regulated by DYRK3. Dissolution of membraneless organelles at the onset of mitosis is also required to release mitotic regulators, such as ZNF207, from liquid-unmixed organelles where they are sequestered and keep them dissolved during mitosis. Regulates mTORC1 by mediating the dissolution of stress granules: during stressful conditions, DYRK3 partitions from the cytosol to the stress granule, together with mTORC1 components, which prevents mTORC1 signaling. When stress signals are gone, the kinase activity of DYRK3 is required for the dissolution of stress granule and mTORC1 relocation to the cytosol: acts by mediating the phosphorylation of the mTORC1 inhibitor AKT1S1, allowing full reactivation of mTORC1 signaling. Also acts as a negative regulator of EPO-dependent erythropoiesis: may place an upper limit on red cell production during stress erythropoiesis. Inhibits cell death due to cytokine withdrawal in hematopoietic progenitor cells.
Synonyms: REDK; RED; hYAK3-2; DYRK5
Tractability: Small molecule: a structure with a bound ligand is known; a high-quality ligand is known; it belongs to a druggable protein family. PROTAC: UniProt records ubiquitination sites on it; ubiquitination databases record sites on it; a small molecule that binds it is known.
Target class: Enzyme; Protein Kinase; Kinase; CMGC protein kinase DYRK family; CMGC protein kinase group; CMGC protein kinase Dyrk2 subfamily
Gene: Protein-coding gene on chromosome 1 (206,635,536 to 206,684,419, forward strand). Ensembl gene ENSG00000143479.
Subcellular location: Nucleus; Cytoplasm; Nucleus speckle; Cytoplasmic granule; Cytoplasm, cytoskeleton, microtubule organizing center, centrosome
Subcellular location (Human Protein Atlas): Nucleoplasm; Cytosol
Gene Ontology:
Molecular function: ATP binding; magnesium ion binding; protein kinase activity; protein serine kinase activity; protein serine/threonine kinase activity; protein tyrosine kinase activity; protein serine/threonine/tyrosine kinase activity
Biological process: erythrocyte differentiation; nuclear speck organization; organelle disassembly; positive regulation of cell cycle G2/M phase transition; protein phosphorylation; regulation of cellular response to stress; regulation of TORC1 signaling; stress granule disassembly; negative regulation of apoptotic process
Cellular component: cytoplasm; cytoplasmic stress granule; nuclear speck; nucleoplasm; nucleus; pericentriolar material; cytoskeleton; centrosome
Genetic constraint (gnomAD): Loss-of-function variants: 29 observed, 38.66 expected, observed/expected ratio (o/e) 0.75, 90% interval 0.56 to 1.02. The upper end of that interval is the gene's LOEUF score, 1.02, which puts it in group 4 of 6, group 1 being the genes least tolerant of losing a copy. Missense variants: 693 observed, 750.61 expected, observed/expected ratio (o/e) 0.92, 90% interval 0.87 to 0.98. Synonymous variants: 270 observed, 269.26 expected, observed/expected ratio (o/e) 1, 90% interval 0.91 to 1.11.
Homologues: Orthologues: chimpanzee DYRK3 (99% identical), dog DYRK3 (95% identical), macaque DYRK3 (95% identical), guinea pig DYRK3 (92% identical), rabbit DYRK3 (90% identical), mouse Dyrk3 (89% identical), rat Dyrk3 (88% identical), pig DYRK3 (85% identical), tropical clawed frog dyrk3 (66% identical), zebrafish dyrk3 (63% identical), Drosophila melanogaster mnb (26% identical), Caenorhabditis elegans mbk-1 (24% identical), and 2 more. Paralogues in human: DYRK2 (60% identical), DYRK4 (40% identical), DYRK1A (26% identical), HIPK2 (26% identical), HIPK3 (26% identical), DYRK1B (24% identical), HIPK1 (24% identical), CLK4 (21% identical), CLK1 (21% identical), CLK3 (21% identical), HIPK4 (19% identical), CLK2 (19% identical).
Diseases named in the same sentence as DYRK3 in open-access papers:
DYRK3 is named in the same sentence as 30 diseases in open-access papers, as found by Europe PMC text mining. Sharing a sentence is not in itself a finding about the gene and the disease. The quoted sentences say what the papers report.
glioblastoma (5 papers, 2021 to 2024). The most malignant astrocytic tumor (WHO grade IV). "Another example, DYRK3, a dual-specificity kinase, contributes to glioblastoma malignancy, and RAP2A increases the migration and invasion of osteosarcoma cell lines." (PMID 37958718, 2023). "Some studies have indicated limited physiological roles and substrates of DYRK3, including promotion of glioblastoma, requirement in influenza virus replication, and coupling of stress granule condensation with mammalian target of rapamycin complex 1 signaling." (PMID 36585413, 2022). "DYRK3 was recently reported to be involved in glioblastoma multiform invasion and migration." (PMID 35454940, 2022). "In addition, radiation-induced DYRK3 expression promotes mitochondrial fission by mTORC1-dependent DRP1 activation, resulting in the promotion of brain tumors such as glioblastoma multiform." (PMID 36585413, 2022). "Regarding the physiological association between DYRK3 and cancer, a recent study discovered that radiation-induced expression of DYRK3 leads to increased mitochondrial fission through mTORC1-dependent DRP1 activation, thereby promoting brain tumors like glioblastoma multiforme (GBM)." (PMID 38519031, 2024).
hepatocellular carcinoma (5 papers, 2021 to 2023). A malignant tumor that arises from hepatocytes. "DYRK3 is reported to inhibit hepatocellular carcinoma progression through metabolic reprogramming mechanisms." (PMID 33804169, 2021). "Conversely, the low phosphorylation of steroid receptor coactivator protein 3 (SRC-3) by DYRK3 promoted purine metabolism and hepatocellular carcinoma progression." (PMID 33804169, 2021). "For example, DYRK3 acts as a tumor suppressor in other cancers such as hepatocellular carcinoma." (PMID 36585413, 2022). "In cases of hepatocellular carcinoma (HCC), DYRK3 expression was significantly lower compared to normal controls." (PMID 38139175, 2023).
glioma (4 papers, 2010 to 2024). A benign or malignant brain and spinal cord tumor that arises from glial cells (astrocytes, oligodendrocytes, ependymal cells). "In gliomas, the expression of DYRK3 and CLK3 correlated with worse survival, while DYRK1A, DYRK2 and CLK1 were associated with better disease outcomes." (PMID 38398225, 2024). "Compellingly, DYRK3 is the only DYRK family member that is correlated with glioma grade in the TCGA database." (PMID 33804169, 2021). "Some of these, such as DYRK3, play a role in cell growth and development in the glioma cell line, whereas LIMK2 is involved in stress fiber and focal adhesion formation and membrane blebs during the apoptotic process." (PMID 21637621, 2010). "Furthermore, two glioma databases suggest patients with high DYRK3 expression have a median survival period that is roughly five times shorter than those with low DYRK3 expression (21.3 vs. 105.2 or 17.8 vs. 83.1 months, respectively." (PMID 33804169, 2021). "Thus, DYRK3 mRNA was found significantly increased in highly invasive NSCLC cell lines compared with low invasive lines, while a strong DYRK3 expression was positively correlated with survival in glioma patients." (PMID 32751160, 2020). "We found that within the TCGA database DYRK3 mRNA levels are remarkedly high in GBM patients, as compared to both normal controls and other low-grade gliomas." (PMID 33804169, 2021).
brain tumors (3 papers, 2021 to 2024). "While DYRK family member functions have been reported in other tumors, to our knowledge this the first report of DYRK3 involvement in brain tumor progression." (PMID 33804169, 2021). "Although a role for DYRK3 in brain tumors has not been reported, one previous study showed DYRK3 expression increased neuron dendrite growth, implicating DYRK3 involvement in nervous tissues." (PMID 33804169, 2021).
neuroblastoma (3 papers, 2023 to 2024). Neuroblastoma (NB) is the most common solid, extracranial childhood tumor. "DYRK3 has recently emerged as a key regulator of several biomolecular condensates and has been linked to the hypoxic response of neuroblastoma cells." (PMID 38255303, 2024). "Additionally, the expression of DYRK3 is highly increased in neuroblastoma and closely associated with decreased survival in neuroblastoma patients." (PMID 38519031, 2024). "Additionally, DYRK3 expression has been associated with a potential role in differentiation and hypoxic control of neuroblastoma cell lines within in vitro studies." (PMID 37532697, 2023). "Efficient and specific downregulation of DYRK3 was confirmed by quantitative Real-Time PCR (RT-qPCR), demonstrating a critical role for DYRK3 in neuroblastoma cell homeostasis." (PMID 38255303, 2024). "We identified the DYRK3 kinase as a critical mediator of neuroblastoma cell proliferation and in vivo tumor growth." (PMID 38255303, 2024). "Our data suggest a role for DYRK3 as a regulator of the neuroblastoma-specific protein CAMKV, which is also required for neuroblastoma cell proliferation." (PMID 38255303, 2024). "The same coimmunoprecipitation (co-IP) experiment was performed using human neuroblastoma SH-SY5Y cells, and immunoblot analysis of the anti-Myc immunocomplexes with anti-Flag antibodies also showed that DYRK3 binds to p62." (PMID 38519031, 2024). "Our data strongly support the idea that inhibition of DYRK3 and/or CAMKV in neuroblastoma cells could constitute an innovative and highly specific intervention to fight against this dreadful cancer." (PMID 38255303, 2024). "To investigate in more detail the relation between DYRK3 levels and neuroblastoma pathophysiology, we knocked down its expression by means of three specific shRNA-expressing lentiviral clones (shDYRK3-1/2/3) vs. a non-targeting control (shCtrl) in two different NB cell lines." (PMID 38255303, 2024).
Oral Squamous Cell Carcinoma (2 papers, 2023 to 2026). "Our studies indicate that the heightened presence of DYRK3 leads to a substantial increase in proliferation, migration, invasion, colony formation, and sphere formation in oral squamous cell carcinoma (OSCC) cells." (PMID 38139175, 2023). "Our study sheds light on the pivotal function of the DYRK3 gene, particularly its role as a crucial kinase in the context of oral squamous cell carcinoma (OSCC)." (PMID 38139175, 2023). "This novel insight suggests that the dysregulation of the PAICS/DYRK3 axis may contribute to the acquisition of radioresistance and the metastatic potential of oral squamous cell carcinoma." (PMID 38139175, 2023). "This knowledge opens new avenues for further research on the PAICS/DYRK3 axis as a potential therapeutic target and may ultimately contribute to the development of novel treatment strategies for patients with oral squamous cell carcinoma." (PMID 38139175, 2023). "This dysregulation of the PAICS/DYRK3 axis serves as a key modulator, influencing treatment effectors and contributing to tumorigenicity, disease progression, and therapy evasion in patients with oral squamous cell carcinoma." (PMID 38139175, 2023). "The results obtained from our experimental investigations have provided compelling evidence supporting the critical involvement of DYRK3 and PAICS in oral squamous cell carcinoma (OSCC)." (PMID 38139175, 2023).
adenoma (1 paper, 2013). A neoplasm arising from the epithelium. "In some cases, these genes were uniquely up-regulated in residual tumors (e.g., Setd1a, Dyrk3), while in other cases the genes were up-regulated in both residual and untreated adenoma tumors (e.g., Suv39h1, Mll1)." (PMID 23520493, 2013).
anemia (1 paper, 2017). A reduction in the number of red blood cells, the amount of hemoglobin, and/or the volume of packed red blood cells. "While Dyrk3−/− mice surprisingly present without a hematological phenotype, they develop increased numbers of red blood cells under conditions of anemia, suggesting that DYRK3 functions as a negative regulator of erythropoiesis." (PMID 29615569, 2017).
blood disease (1 paper, 2025). A disease that occurs in the blood. "In terms of disease association, DYRK3 is closely related to various blood diseases, such as hereditary spherocytosis, and some neurological conditions." (PMID 40313599, 2025).
cervical carcinoma (1 paper, 2024). A carcinoma arising from either the exocervical squamous epithelium or the endocervical glandular epithelium. "Among the different cancer cell lines tested, including human cervical carcinoma cells (HeLa), human embryonic kidney cells (HEK), human prostate cells (RWPE-1), and melanoma cell lines (SK-Mel-28, SK-Mel-5, UACC257, and UACC62), the highest expression of DYRK3 was observed in melanoma cell lines." (PMID 38519031, 2024).
cognitive deficits (1 paper, 2022). "Further studies are required to examine whether DYRK3-mediated phosphorylation of SNAPIN could reduce the synaptic production of Aβ, and attenuate the synapse loss and/or cognitive deficits seen in patients with AD." (PMID 36585413, 2022).
head and neck cancer (1 paper, 2023). A primary or metastatic malignant neoplasm affecting the head and neck. "Furthermore, we examined the expression of the DYRK3/PAICS axis in different stages of head and neck cancer to gain insights into the molecular regulatory changes occurring during cancer progression." (PMID 38139175, 2023).
lymph node metastasis (1 paper, 2024). "Notably, lymph node status exhibited a significant association with DYRK3 expression levels (P = 0.010), indicating a correlation between DYRK3 and the presence of lymph node metastasis." (PMID 38529261, 2024).
melanoma (1 paper, 2024). A malignant, usually aggressive tumor composed of atypical, neoplastic melanocytes. "We also found that DYRK3-mediated phosphorylation of p62 at Thr-269 enhanced the growth of melanoma cell lines and melanoma progression." (PMID 38519031, 2024). "Conversely, DYRK3 knockdown or blockade of p62-T269 phosphorylation inhibited melanoma growth, colony formation, and cell migration." (PMID 38519031, 2024). "We then investigated the colocalization of DYRK3 and phospho-p62 at T269/S272 in SK-Mel-28 melanoma cells." (PMID 38519031, 2024). "The present study further suggests that high expression of p62 and DYRK3 in melanoma can promote cancer growth via the mTOR pathway." (PMID 38519031, 2024). "Interestingly, our preliminary analyses of several cancer databases have revealed strong expression of both DYRK3 and p62 in melanoma cell lines." (PMID 38519031, 2024). "In addition to these genes, the present study proposes two additional markers for melanoma progression: p62 and DYRK3." (PMID 38519031, 2024). "Next, we examined whether the intracellular DYRK3 protein level could be increased in various melanoma cell lines." (PMID 38519031, 2024). "We then examined whether there would be a biochemical and/or functional interaction between DYRK3 and p62 in mammalian cells, and if so, how they might affect melanoma progression." (PMID 38519031, 2024). "Based on the findings that the upregulation of DYRK3 in melanoma skin cancer cells and dysregulation of the mTOR pathway are closely associated with various types of human tumors, we investigated the effect of DYRK3-mediated activation of the mTORC1 pathway on melanoma cancer cell growth." (PMID 38519031, 2024). "Taken together, these results indicate that the expression levels of DYRK3 and p62 are higher in melanoma cells than other cancer cell lines, suggesting that DYRK3 and p62 may play a role in the progression of melanoma." (PMID 38519031, 2024). "Our data suggest that DYRK3 directly phosphorylates p62 at Thr-269, stimulating the activation of the mTORC1-mediated downstream signaling pathway and ultimately leading to an increase in the oncogenic function of p62 in melanoma." (PMID 38519031, 2024). "This study aimed to investigate whether DYRK3 interacts with p62, and how this affects melanoma progression, particularly in melanoma cell lines." (PMID 38519031, 2024). "Interestingly, it was observed that the expression of DYRK3, as well as p62 (a multifunctional signaling protein), is highly enhanced in most melanoma cell lines." (PMID 38519031, 2024). "Furthermore, when we established human SK-Mel-28 melanoma cells stably expressing DYRK3, they exhibited much enhanced phosphorylation of p62, S6K, and 4EBP1 compared to mock-transfected control cells." (PMID 38519031, 2024). "Moreover, we examined whether there is an interaction between DYRK3 and p62 in several melanoma cells and found that endogenous DYRK3 binds to endogenous p62 in melanoma SK-Mel-28 and UACC257 cell lines." (PMID 38519031, 2024). "In conclusion, we demonstrated that DYRK3 phosphorylates p62, positively modulating the p62-TRAF6-mTORC1 pathway in melanoma cells." (PMID 38519031, 2024). "Since all the melanoma cell lines we used exhibited higher levels of p62 and DYRK3, this characteristic appears to be independent of the BRAF-V600E mutation." (PMID 38519031, 2024).
oral cancer (1 paper, 2023). "Finally, we used the GSE42743 data set of Gene Expression Omnibus (GEO) to analyze the expression profile of DYRK2 and DYRK3 genes in oral cancer and adjacent normal tissues." (PMID 38139175, 2023).